CPTP (ceramide-1-phosphate transfer protein)
Description:
Mediates the intracellular transfer of ceramide-1-phosphate (C1P) between organelle membranes and the cell membrane. Required for normal structure of the Golgi stacks. Can bind phosphoceramides with a variety of aliphatic chains, but has a preference for lipids with saturated C16:0 or monounsaturated C18:1 aliphatic chains, and is inefficient with phosphoceramides containing lignoceryl (C24:0). Plays a role in the regulation of the cellular levels of ceramide-1-phosphate, and thereby contributes to the regulation of phospholipase PLA2G4A activity and the release of arachidonic acid. Has no activity with galactosylceramide, lactosylceramide, sphingomyelin, phosphatidylcholine, phosphatidic acid and ceramide. C1P transfer is stimulated by phosphatidylserine in C1P source vesicles. Regulates autophagy, inflammasome mediated IL1B and IL18 processing, and pyroptosis, but not apoptosis.
Synonyms: GLTPD1; MGC10334
Tractability: Small molecule: a structure with a bound ligand is known. Antibody: UniProt places it where antibodies can reach, with high confidence; its Gene Ontology location is reachable by antibodies, with medium confidence. PROTAC: ubiquitination databases record sites on it.
Gene: Protein-coding gene on chromosome 1 (1,324,756 to 1,328,897, forward strand). Ensembl gene ENSG00000224051.
Subcellular location: Cytoplasm, cytosol; Golgi apparatus, trans-Golgi network membrane; Cell membrane; Endosome membrane; Nucleus outer membrane
Subcellular location (Human Protein Atlas): Cytosol; Flagellar centriole; Mid piece; Perinuclear theca
Pathways (Reactome):
Transport of small molecules: Glycosphingolipid transport
Gene Ontology:
Molecular function: ceramide 1-phosphate binding; ceramide 1-phosphate transfer activity; phospholipid binding; lipid transfer activity
Biological process: ceramide 1-phosphate transport; glycolipid transport; negative regulation of autophagy; negative regulation of interleukin-1 beta production; negative regulation of NLRP3 inflammasome complex assembly; ceramide transport; intermembrane lipid transfer
Cellular component: cytosol; endosome membrane; nuclear outer membrane; plasma membrane; trans-Golgi network membrane; cytoplasm; Golgi apparatus
Genetic constraint (gnomAD): Loss-of-function variants: 10 observed, 9.23 expected, observed/expected ratio (o/e) 1.08, 90% interval 0.66 to 1.75. That is too few expected variants to judge how well the gene tolerates losing a copy. Missense variants: 335 observed, 286.67 expected, observed/expected ratio (o/e) 1.17, 90% interval 1.07 to 1.28. Synonymous variants: 166 observed, 134.57 expected, observed/expected ratio (o/e) 1.23, 90% interval 1.09 to 1.4.
Homologues: Orthologues: chimpanzee CPTP (100% identical), macaque CPTP (94% identical), dog CPTP (82% identical), mouse Cptp (79% identical), guinea pig CPTP (78% identical), rat Cptp (77% identical), tropical clawed frog cptp (57% identical), zebrafish cptp (56% identical), zebrafish gltpd2b (36% identical), zebrafish gltpd2a (33% identical), Caenorhabditis elegans tag-296 (25% identical), Caenorhabditis elegans F49D11.10 (24% identical), and 2 more. Paralogues in human: GLTPD2 (36% identical), PLEKHA8 (23% identical), GLTP (16% identical), CERT1 (13% identical), PLEKHA3 (9% identical).
Diseases named in the same sentence as CPTP in open-access papers:
CPTP is named in the same sentence as 15 diseases in open-access papers, as found by Europe PMC text mining. Sharing a sentence is not in itself a finding about the gene and the disease. The quoted sentences say what the papers report.
colon tumor (1 paper, 2022). "Another study demonstrated that CPTP is associated with breast and colon tumor progression 37; however, the role, underlying mechanism, transcriptional regulation and disease-relevant clinical research of CPTP in cancer have not been reported." (PMID 35982909, 2022).
cancer (2 papers, 2020 to 2022). A tumor composed of atypical neoplastic, often pleomorphic cells that invade other tissues. "Notably, CPTP has been considered as a promising molecule of cancer 52; however, the role and molecular mechanism involved remain elusive." (PMID 35982909, 2022).
tumor (2 papers, 2022). "CPTP expression was also associated with tumor TNM stage, suggesting that CPTP expression is related to dismal prognosis in patients with PC." (PMID 35982909, 2022). "CPTP knockdown triggers inflammation and autophagy 36, and CPTP has been associated with tumor development and progression." (PMID 35982909, 2022). "The expression levels of SH3BP1, KDM5B (involved in serine/threonine kinase activity pathway) and PI4KA (belongs to inositol phosphate metabolism pathway) were notably increased in cells overexpressing CPTP, and are associated with tumor progression." (PMID 35982909, 2022). "Consistent with the results from TCGA, CPTP protein expression levels were higher in tumor tissues than normal." (PMID 35982909, 2022). "In this research, CPTP was first confirmed to act as a pro-tumor molecule and plays an important role in PC." (PMID 35982909, 2022). "After 28 days, the mice with overexpression of CPTP had a higher mean tumor weight (101.82±59.99 mg versus the control group 33.4±19.58 mg; p=0.0152) and volume (269.25±111.93 mm3 versus 83.87±65.36 mm3; p=0.0095)." (PMID 35982909, 2022). "CPTP was found to be involved in pyroptosis, and while its pro-tumor function in DLBCL was discovered in our study, HTRA1, RBBP7, NFE2L2 and SCAF11 were found to be tumor suppressive." (PMID 36551263, 2022). "On the other hand, CPTP is a direct target of the tumor suppressor, microRNA-328 35, suggesting that CPTP may be associated with tumorigenesis." (PMID 35982909, 2022). "This suggested that CPTP expression has a high degree of accuracy in tumor prediction." (PMID 35982909, 2022). "Tumor weight (14.52±7.84 versus 193.62±100.47 mg) and volume (24.20±6.59 versus 344.12±92.79 mm3) was notably decreased in mice transfected with cells and stable knockdown of CPTP expression compared with that in mice transfected with control cells." (PMID 35982909, 2022). "Notably, the levels of carnitine (14:0/14:1/16:0/16:1/18:1-carniting) and pro-tumor molecular lyso-phosphatidylcholines (C16:1/C18:1-LPC) were increased in cells expressing CPTP and decreased in cells with CPTP expression knocked down." (PMID 35982909, 2022).
CPTP also shares sentences with these, for which no sentence is quoted: pancreatic cancer (2 papers); pulmonary embolism (2); acute pancreatitis (1); breast carcinoma (1); colorectal cancer (1); deep vein thrombosis (1); lung carcinoma (1); multiple myeloma (1); non-Hodgkin lymphoma (1); post-thrombotic syndrome (1); prostate carcinoma (1); venous thromboembolism (1).